LEP (leptin)
Diseases named in the same sentence as LEP in open-access papers (continued):
Sharing a sentence is not in itself a finding about the gene and the disease.
Obesity (continued). "In the LCF group, the elevated leptin levels were also accompanied by higher concentrations of visfatin—the adipocytokine associated with obesity and visceral fat." (PMID 23744123, 2013). "The leptin-deficient ob/ob mouse was used as a genetically induced obesity mouse model and the B6 mouse, a commonly studied experimental model of metabolic diseases, was employed as a control." (PMID 24098417, 2013). "We also have observed strong statistical evidence for an association of rs8061518 in intron 3 of the gene with decreased risk of obesity and low concentration of leptin." (PMID 24289790, 2013). "Increased serum concentration of leptin is correlated with obesity, and a high level of leptin is associated with breast cancer risk." (PMID 23750285, 2013). "A large study of over 1000 patients suggested that elevated adiponectin and resistin (another adipokine) were only weakly associated with OA and obesity but there was a stronger positive correlation between OA and obesity and leptin." (PMID 24304704, 2013). "As to glucoregulatory functions, increased leptin levels are associated with obesity and type 2 diabetes, while decreased ghrelin levels are associated with obesity and insulin resistance rather than type 2 diabetes." (PMID 23579596, 2013). "Leptin production is increased in obesity and hyperleptinemia that reflects leptin resistance enhances metabolic risk." (PMID 23690663, 2013). "Neonatal treatment with leptin, from P3 to P13, can also reduce the hyperleptinemia, hyperinsulinemia, hyperphagia, and obesity associated with in utero growth restriction and subsequent high fat diet, albeit with some sex differences." (PMID 23785312, 2013). "In summary, reduced hepatic mitochondrial content and function and an upregulation in de novo lipogenesis contribute to obesity-associated NAFLD in the leptin-deficient Ob/Ob mouse." (PMID 23401753, 2013). "Previous studies also reported that high leptin or leptin resistance status was associated with obesity, MetS and CVD, which is consistent with our results." (PMID 23555948, 2013). "In the leptin-deficient ob/ob mice, hypothalamic leptin signaling is drastically reduced and hyperphagia develops leading to obesity." (PMID 23966982, 2013). "These variations in relative risk suggest that leptin resistance is an additional important mediator of obesity’s risk, an important question for future epidemiologic investigation." (PMID 23806173, 2013). "In this study, we examined adiponectin and leptin development in Mexican American children at high risk of obesity." (PMID 24205046, 2013). "Consistent with its role in maintaining food intake and or body weight, a deficiency in leptin results in substantial obesity in mouse as well as in human supporting a role of leptin in energy homeostasis." (PMID 23557393, 2013). "Formerly, immune dysfunction has been shown to be associated with obesity, whereas leptin concentrations were recently found to be higher in Africans, compared with Caucasians, after adjustment for BMI and other factors." (PMID 24146750, 2013). "Leptin resistance that involves impairment in leptin transport, leptin signaling, and/or the neurocircuitry of energy balance is a risk factor for obesity." (PMID 23232494, 2013). "Blocking the postnatal leptin surge results in long-term leptin insensitivity and increased susceptibility to diet-induced obesity during adulthood." (PMID 23579596, 2013). "Leptin signaling impairment, frequently found in obesity, has been associated with sensitivity to diet induced obesity, especially when animals are exposed to high fat/highly palatable diets." (PMID 23544111, 2013). "Cytokine with mostly multipotential performance is leptin, encoded by the so-called obesity gene—OB, which affects body mass regulation through hypothalamus influence on appetite and energy expenditure." (PMID 24319457, 2013).
Obesity (continued). "Based on epidemiological and clinical studies, an association between obesity and allergy has been postulated, therefore leptin was investigated as a possible mediator of this link." (PMID 24084730, 2013). "In a mice model of diet-induced obesity, the increase in leptin levels correlates with a loss in PVAT-derived NO and eNOS." (PMID 24307898, 2013). "Both disorders share complex interactions, among which are increased work of breathing related to (central) obesity, alterations of ventilatory drive, various associated sleep breathing disorders and neurohormonal changes such as leptin resistance." (PMID 24256627, 2013). "Congenital leptin deficiency, caused by a very rare mutation in the gene encoding leptin, leads to severe obesity, hyperphagia and impaired satiety." (PMID 23799059, 2013). "Obesity is an important risk factor for intervertebral disc degeneration and leptin is a biomarker of obesity." (PMID 23335226, 2013). "For example, ARC explants from diet induced obesity-susceptible rats are less responsive to leptin, developing less neurite outgrowth after leptin application than controls." (PMID 23785312, 2013). "In this context, the participation of SOCS3 in the negative-feedback mechanism of leptin signaling has been proposed to underlie the development of leptin resistance in relation to the hyperleptinemia observed during obesity." (PMID 24151494, 2013). "In women from rural areas, concentrations of zinc and vitamin C were associated with obesity, adiposity and leptin concentrations." (PMID 24335710, 2013). "Experimentally, a cause-effect relationship of orally-taken leptin during early life in preventing obesity and other metabolic alterations in later life was first shown in neonatal rats supplemented with physiological doses of leptin throughout lactation." (PMID 24062695, 2013). "In transgenic animal models, such as leptin-deficient (ob/ob) mice and LepRb-deficient (db/db) mice, exhibit the development of marked obesity, insulin resistance, hyperinsulinemia, impaired glucose homeostasis, and diabetes." (PMID 23579596, 2013). "Disruption in leptin surge during perinatal life in rodents has been demonstrated to have lasting consequences by altering the capacity to respond to leptin in adulthood, thus predisposing animals to obesity." (PMID 24312379, 2013). "Obesity is frequently associated with elevated circulating leptin levels and an increased risk to develop cardiac hypertrophy or heart failure." (PMID 23841921, 2013). "The first genetic evidence of congenital leptin deficiencies in humans with severe obesity emerged in 1997." (PMID 23579596, 2013). "The weight loss of the mice with diet-induced obesity was associated with reductions in both food consumption and plasma leptin levels." (PMID 23092275, 2013). "The receptor for leptin, an obesity-associated adipokine that was significantly elevated in our obese patient group, has also been shown to crosstalk with IGF-1R, resulting in greater IGF-1R activation and an upregulation of Akt and ERK1/2 phosphorylation." (PMID 23880059, 2013). "Circulating leptin concentrations are increased in obesity, and these increased levels are associated with the development of inflammation, insulin resistance, and subclinical coronary atherosclerosis." (PMID 24376307, 2013). "More recently, arcuate-specific Pomc mutant mice have been generated, which have rapid post-weaning obesity and associated hyperglycemia and elevated leptin." (PMID 23649822, 2013). "Leptin deficient (ob/ob) and leptin receptor deficient (db/db) mice exhibit obesity, hyperglycemia, hyperinsulinema and hyperglucagonemia." (PMID 23936486, 2013). "This is suggestive of a partial role for leptin in obesity asthma association as observed in previous studies." (PMID 24025484, 2013). "Disruptions in the leptin signaling systems are often associated with hyperphagia and consequently obesity." (PMID 23966982, 2013).
Obesity (continued). "To address molecular mechanisms underlying obesity development, we examined patterns of critical metabolism-related hormones, adiponectin and leptin (adipokines), over childhood." (PMID 24205046, 2013). "Obesity is a major risk factor for diabetes and is typically associated with hyperleptinemia and a state of leptin resistance." (PMID 23936486, 2013). "We have observed strong statistical evidence for an association of rs8061518 in intron 3 of the gene with decreased risk of obesity and low concentration of leptin." (PMID 24289790, 2013). "Leptin deficiency in ob/ob mice is associated with hyperphagia, obesity as well as insulin resistance and diabetes." (PMID 23557393, 2013). "Obesity is associated with elevated circulating leptin levels and hypothalamic resistance to the weight-reducing effects of the adipokine, whereas the existence of a peripheral (e.g. cardiac) leptin resistance is controversial." (PMID 23841921, 2013). "Genetic deficiency of leptin or its receptor cause obesity and obesity-associated diabetes mellitus." (PMID 24049662, 2013). "This retention of leptin-mediated inhibitory responses is consistent with the modest level of obesity in Magel2-null mice compared with leptin-deficient Lepob or leptin receptor null Leprdb mice." (PMID 23341784, 2013). "Leptin is a small adipokine (precursor: 167 amino acids and mature protein: 146 amino acids, 16 kDa) encoded by the obesity (ob or LEP) gene." (PMID 24202338, 2013). "In contrast, previous work examining sympathetic activation in obese db/db mice indicated an increase in renal sympathetic nerve activity (RNSA) with leptin-deficient obesity, but a dissociation of obesity and RNSA in MC4R KO mice." (PMID 24400148, 2013). "This study aims to evaluate serum leptin and adiponectin concentrations in asthmatic school children to investigate their association with obesity and the degree of asthma control." (PMID 24454412, 2013). "DGKZ has been implicated as a member of the downstream leptin signaling pathway and reduced expression or activity within the hypothalamus has been associated with obesity." (PMID 23758707, 2013). "In the central nervous system obesity-associated inflammation can disrupt leptin hypothalamic action through IKKβ/NFkβ regulation of SOCS-3 (suppressor of cytokine signaling-3), a key inhibitor of leptin signaling." (PMID 23672628, 2013). "Leptin administration into the CNS of mice or rats increases alveolar ventilation and dysfunction in leptin signaling has been implicated in the hypoventilation that can accompany obesity." (PMID 23408476, 2013). "HFD-induced obesity is also known to be strongly associated with the levels of adipokines such as leptin and adiponectin, both of which are secreted from WAT." (PMID 24376752, 2013). "The association between polymorphism of obesity-related genes (LEP, LEPR and PON1) and breast cancer risk has been investigated." (PMID 23826274, 2013). "The aim of the present study was to evaluate serum leptin and adiponectin concentrations in asthmatic school children and to investigate their association with obesity and degree of asthma control." (PMID 24454412, 2013). "The LEP and its receptor gene were newly found to play a role in carcinogenesis especially in obesity-associated malignancies." (PMID 23593308, 2013). "In fact, the associations of CD68 gene expression with fasting glucose, leptin and adipogenic gene expression were closely dependent on obesity." (PMID 23951013, 2013). "A cohort study has explained this issue as rapid infancy weight gain was associated with leptin resistance, one of the mechanism thought to underlie obesity." (PMID 24144201, 2013). "Here we examined genes and proteins involved in hepatic oxidation and lipogenesis in 14-week-old leptin-deficient Ob/Ob mice, a commonly studied model of obesity and hepatic steatosis." (PMID 23401753, 2013).
Obesity (continued). "Other genetic models of obesity and diabetes, including the leptin- or leptin receptor-deficient obese mice (ob/ob or db/db), are also more susceptible to alkylation-induced ACF." (PMID 23560112, 2013). "Dosage sensitivity is a feature of a number of metabolic related genes, e.g., expression of the mouse OB1 gene (homolog of the human gene encoding leptin) in relation to obesity." (PMID 24039719, 2013). "Future work is needed in human samples to validate the biomarker signatures of obesity identified in our study and to characterize leptin-deficient obesity, which can be further used for anti-obesity drug development." (PMID 24098417, 2013). "Mutations in the human leptin gene are associated with hypogonadism and morbid obesity, and mutations in the human leptin receptor gene causes obesity and pituitary dysfunction." (PMID 23533722, 2013). "Obesity is associated with hyperleptinemia and hypothalamic leptin resistance as well as an increased risk to develop cardiac hypertrophy and heart failure." (PMID 23841921, 2013). "Here, we report the metabolomic analysis of obesity by using leptin-deficient ob/ob mice based on the gender." (PMID 24098417, 2013). "Our data suggest that adiponectin and leptin levels in patients with T2DM are more associated with obesity and less with diabetes." (PMID 24634792, 2013). "Leptin and adiponectin are secreted from adipose tissue and are linked to obesity, metabolic morbidity, insulin resistance and energy homeostasis." (PMID 23940841, 2013). "Leptin resistance, the hallmark of high-Fat diet induced obesity model, is a phenomenon in which circulating leptin levels decrease in response to target tissues, such as adipose tissue, muscles, liver, and hypothalamus." (PMID 23864899, 2013). "In conclusion, obesity associated with increased serum leptin and TNF-α levels enhance eosinophil chemotaxis and adhesion in asthmatic children and adolescents." (PMID 23773659, 2013). "Mechanistically, the defected leptin signaling in hypothalamus associated with obesity probably confers partially at least for the altered striatal DA homeostasis upon maternal overnutrition." (PMID 24223863, 2013). "In this study, our 1H-NMR-based metabolomic profiling of obesity using leptin-deficient ob/ob mouse has shown metabolic changes and gender variations in obesity." (PMID 24098417, 2013). "Many studies evaluating the effects of functional food components on the pathogenesis of obesity-related metabolic disorders have been carried out in genetic leptin-resistant db/db mice and leptin-deficient ob/ob mice." (PMID 23406154, 2013). "In conclusion, our study findings indicate that among asthmatic school children higher serum leptin and lower adiponectin levels were significantly associated with obesity." (PMID 24454412, 2013). "Similar increases in susceptibility to diet induced obesity have been reported in neonatal rat pups administered leptin at a similar dose (PD3-13)." (PMID 23423541, 2013). "Another commonly studied model of hyperphagia-induced obesity and insulin resistance is the leptin-deficient Ob/Ob mouse." (PMID 23401753, 2013). "In fact, impaired leptin action in the central nervous system (CNS) has been implicated in both obesity and depression and a potential link between these conditions have been suggested." (PMID 23251447, 2012). "The db/db mouse, with an inactivating mutation in the Ob-Rb receptor, has an obese phenotype, and leptin-deficient ob/ob mice exhibit hyperphagia and obesity, which can be reversed by leptin administration." (PMID 22899902, 2012). "We propose that any mechanism that increases SOCS3 protein expression beyond a certain level in POMC neurons will cause long-term leptin resistance in those cells and eventually to obesity." (PMID 22276206, 2012). "While the strongest role for leptin is as a marker for improved outcomes, lowering elevated leptin has been associated with improved obesity and clinical outcomes." (PMID 22485140, 2012).
Obesity (continued). "Inactivating mutations of leptin or leptin receptor gene result in the body's false perception of starvation and subsequent hyperphagia, decreased energy expenditure, and severe obesity." (PMID 22518191, 2012). "Mutations in leptin and leptin receptor genes have been associated with mild to extreme obesity phenotype in human population." (PMID 22474595, 2012). "In numerous model of diet induced obesity, a hallmark of leptin resistance is the impairment of central leptin signalling mostly in hypothalamic neurons but the mechanisms of leptin resistance remains complex and incompletely understood." (PMID 22291999, 2012). "Animals predisposed to develop obesity on a high-fat diet (which are leptin resistant) have defective neuronal connections." (PMID 22802935, 2012). "The objective of the present study was to determine the suitability of a swine breed with leptin resistance and predisposition to obesity (the Iberian pig) as model for studies on metabolic syndrome and type 2 diabetes." (PMID 22629144, 2012). "Our study provides first evidence for the association of AMD1 variant with obesity and plasma leptin levels in children." (PMID 22496743, 2012). "Both humans and mice with genetic loss of function mutations in either leptin or LepRb manifest severe early onset obesity (, insulin resistance, dyslipidemia and other metabolic, neuro-endocrine and immune dysfunctions." (PMID 22815920, 2012). "Vitamin E has been shown to decrease leptin expression in rats and low vitamin E intake has been associated with the expression of genes associated with obesity, such as SIRT1 variants." (PMID 22703731, 2012). "Further, obesity and colon cancer are frequently associated with systemic hormonal changes, particularly with high serum levels of insulin and leptin, two hormones that are thought to promote cancer initiation and progression." (PMID 23056418, 2012). "We have reported that the combination of these three herbs suppresses the development of insulin resistance in leptin-deficient db/db mouse which is an animal model of obesity-induced T2D." (PMID 22474520, 2012). "Accordingly, we investigated to which extent high leptin levels and low grade inflammation- associated ER stress – two markers linked to obesity – take effect on leptin receptor availability for sOb-R generation." (PMID 22545089, 2012). "As obesity and obesity-linked disorders such as type II diabetes are associated with resistance to leptin, it is feasible that leptin dysfunction plays a role in cognitive impairments in these individuals." (PMID 22254146, 2012). "In obesity mouse models, decreased energy expenditure and increased food intake have been associated with mutations in the leptin system." (PMID 22623906, 2012). "The link between sleep loss and obesity therefore appears more complicated than a simple disruption of leptin metabolism." (PMID 22844441, 2012). "Previous study on the molecular defect underlying the development of obesity in genetically recessive ob/ob mouse led to the discovery of leptin, a cytokine-like factor, produced predominantly in white adipose tissue." (PMID 22992416, 2012). "In spite of its anti-obese effects, serum leptin concentrations are correlated strongly with body mass index, and obesity is associated with hyperleptinemia." (PMID 23270329, 2012). "The purpose of this study was to evaluate the effects of SO consumption in leptin-deficient ob/ob mice, a model of obesity and insulin resistance." (PMID 23209931, 2012). "Despite the evidence that absolute leptin deficiency is seldom a cause of obesity, the importance of leptin in regulation of body weight remains." (PMID 24527265, 2012). "Low birth weight followed by catch-up growth and body fat accumulation during childhood is associated with increased risk of obesity, insulin and leptin resistance and CVD later in life." (PMID 22615820, 2012).